TRIM28 (tripartite motif containing 28)
Diseases named in the same sentence as TRIM28 in open-access papers (continued):
Sharing a sentence is not in itself a finding about the gene and the disease.
osteosarcoma (4 papers, 2017 to 2024). A usually aggressive malignant bone-forming mesenchymal neoplasm, predominantly affecting adolescents and young adults. "In osteosarcoma, TRIM28 promotes the SUMOylation modification of VPS34 by forming a complex with PVT-1 (Plasmacytoma variant translocation-1), further enhancing the ubiquitination and degradation of TSC2, thereby enhancing the self-renewal and stem cell phenotype of osteosarcoma cells." (PMID 39100077, 2024). "Moreover, it was previously demonstrated that TRIM28 downregulation in the U2-OS human osteosarcoma cell line sensitizes these cells to neocarzinostatin, an ionizing radiation mimetic." (PMID 27845900, 2017).
prostate tumors (4 papers, 2017 to 2026). "Overall, these findings suggest that Trim28 deletion in NPp53T prostate tumors results in the derepression of ERVs across numerous genomic loci." (PMID 41508128, 2026). "Although our analysis in this study focused on the expression of ERVs at 1 month after Trim28 deletion in NPp53T prostate tumors, RT-qPCR analysis confirmed persistent ERV expression up to 3 months post-Trim28 deletion." (PMID 41508128, 2026). "We further compared TRIM28 repression of ERVs in NPp53 prostate tumors to embryonic stem cells and neuronal progenitor cells." (PMID 41508128, 2026). "We found Trim28 deletion in prostate tumors led to the expression of ERVs in prostates from both hormonally intact and castrated mice." (PMID 41508128, 2026). "Genes overexpressed in NPp53T prostate tumors included Bglap3 and Ptpn22, which we previously identified as overexpressed in tumor cells upon Trim28 deletion, and granzyme E (Gzme), expressed in cytotoxic T cells." (PMID 41508128, 2026). "We found that Trim28 deletion led to widespread expression of ERVs in prostate tumors from hormonally intact and castrated mice." (PMID 41508128, 2026). "Western blot analysis confirmed three isogenic LNCaP lines corresponding to SPOP mutant, TRIM28-high, and TRIM28-low prostate tumors." (PMID 30479348, 2018). "Our data suggest that Trim28 deletion in prostate tumor epithelial cells may promote an innate immune response." (PMID 41508128, 2026). "We previously also reported increased gene expression of Ptpn22 in prostate tumor epithelial cells after Trim28 deletion, although Ptpn22 expression is not altered after Trim28 deletion in embryonic stem cells, neuronal progenitor cells, or adult liver." (PMID 41508128, 2026). "We also identified Ptpn22 as a gene repressed by TRIM28 in NPp53 prostate tumors, but not in ES cells, neural progenitor cells, or liver." (PMID 41508128, 2026).
renal cell carcinoma (4 papers, 2020 to 2024). "TRIM28 facilitates the ubiquitination and degradation of TFE3, hence preventing the growth of cells that cause renal cell carcinoma." (PMID 39534556, 2024). "Research has shown that overexpression of TRIM28 inhibits the growth of renal cell carcinoma (RCC) cells, and high TRIM28 protein and mRNA expression is associated with better OS in RCC patients." (PMID 39100077, 2024).
metastatic cancer (3 papers, 2014 to 2022). A carcinoma which has spread from the original site of growth to another anatomic site. "In late stage or metastatic cancers, high level of Trim28 contribute to EMT through transcription regulation of epithelial and mesenchymal genes, as a result, cells with high level of Trim28 tend to have a more invasive and metastatic nature." (PMID 24983967, 2014).
skin cutaneous melanoma (3 papers, 2020 to 2021). "Next, we analyzed the association of TRIM28 expression with clinicopathological features of skin cutaneous melanoma (SKCM) patients in TCGA data and observed that TRIM28HIGH patients harbored higher frequency of fraction genome altered (FGA) than TRIM28NORM cohort (p = 1.46e-3)." (PMID 33076560, 2020). "Higher TRIM28 levels were associated with poorer OS in adrenocortical carcinoma, brain lower grade glioma, LUAD, mesothelioma, skin cutaneous melanoma, etc.." (PMID 33091876, 2020). "Firstly, using RNA Seq V2 RSEM data from the cBioportal database for the skin cutaneous melanoma (SKCM) patients (n = 469), we analyzed the distribution of TRIM28 expression in tumor samples resulting in discrimination of 117 samples (25%) with robustly elevated TRIM28 denoted as TRIM28HIGH." (PMID 33076560, 2020).
acute myeloid leukemia (2 papers, 2024 to 2025). Acute myeloid leukemia (AML) is a group of neoplasms arising from precursor cells committed to the myeloid cell-line differentiation.
allergic disease (2 papers, 2022 to 2025). An immune response that occurs following re-exposure to an innocuous antigen, and that requires the presence of existing antibodies against that antigen. "The results suggest that to develop inhibitors of TRIM28 has the translation potential to be used for the treatment of AA and other allergic diseases." (PMID 40391221, 2025). "Therefore, environmental factors responsible for the increasing number of subjects affected by allergy could exert their actions via TRIM28/SETDB1‐ and/or HERV‐driven variations in targeted biologic processes." (PMID 35344298, 2022). "Despite the potential impact of HERVs and of TRIM28 and SETDB1 in triggering and/or maintaining allergic reactions, to the best of our knowledge no studies explored their expressions in allergic patients." (PMID 35344298, 2022).
Anxiety (2 papers, 2010 to 2016). Intense feelings of nervousness, tension, or panic often arise in response to interpersonal stresses. "A recent study of a Trim28 conditional knockout in the forebrain reported heightened anxiety and stress-induced behavior in mutant animals." (PMID 21092094, 2010).
autism (2 papers, 2016 to 2019). Persistent deficits in social interaction and communication and interaction as well as a markedly restricted repertoire of activity and interest as well as repetitive patterns of behavior. "Thus, the correct induction of CTNND2 expression through the reduction of REST and TRIM28 may be crucial for normal neuronal development and the prevention of autism, and TRIM28 may be involved in the regulation of CTNND2 by acting as a corepressor of REST." (PMID 27976729, 2016).
autoimmune disease (2 papers, 2018). A disorder resulting from loss of function or tissue destruction of an organ or multiple organs, arising from humoral or cellular immune responses of the individual to their own tissue constituents. "To further confirm this, we utilized the Trim28fl/flIl17fcre mice to investigate the in vivo function of TRIM28 in Th17-mediated autoimmune disease." (PMID 29651155, 2018). "Here we show that Tripartite motif containing 28 (Trim28) expression in Th17 cells is required for Th17-mediated cytokine production and experimental autoimmune diseases." (PMID 29651155, 2018). "Our study thus suggests TRIM28 to be important for the epigenetic activation during Th17 cell differentiation, and prompts the potential use of epigenetic interventions for Th17-related autoimmune diseases." (PMID 29651155, 2018). "The Lck-related immunity may have further-reaching implications for TRIM28 as several TRIM family members, including TRIM28, have been shown to act as antigens eliciting autoantibody responses in cancer and autoimmune disease." (PMID 29631612, 2018).
B-cell NHLs (2 papers, 2024 to 2025). "Interestingly, the silencing of another Ub E3, TRIM28, has already been shown to enhance sensitivity to BTZ in B-cell non-Hodgkin lymphoma cells resistant to this agent." (PMID 40097385, 2025). "TRIM28 was shown to be upregulated in CTCL and B-cell-NHL patient samples." (PMID 38397043, 2024).
brain inflammation (2 papers, 2022 to 2026). "Their transcription is regulated by TRIM28 and SETDB1, which are involved in the regulation of epigenetic processes, in neural cell differentiation, and brain inflammation." (PMID 42123339, 2026). "HERV activation is regulated by TRIM28 and SETDB1, which are part of the epigenetic mechanisms that organize the chromatin architecture in response to external stimuli and are involved in neural cell differentiation and brain inflammation." (PMID 35682642, 2022).
clear cell renal carcinoma (2 papers, 2020 to 2023). A malignant epithelial neoplasm of the kidney characterized by the presence of lipid-containing clear cells within a vascular network. "Both datasets indicated higher TRIM28 protein (CPTAC) and mRNA (TCGA) levels correlate with better overall survival in patients with clear cell renal carcinoma." (PMID 36935008, 2023).
endometrial cancer (2 papers, 2023). Primary or metastatic malignant neoplasm involving the endometrium (mucous membrane that lines the endometrial cavity). "To directly unveil the functional coupling between TRIM28 and PR/ERα, we performed luciferase reporter assay in Human endometrial cancer cell line (HEC1A)." (PMID 37528140, 2023).
endometriosis (2 papers, 2023 to 2024). The growth of functional endometrial tissue in anatomic sites outside the uterine body. "In summary, we identified a positive correlation between the TRIM28 deletion induced gene signature with human endometrial disorders, such as endometriosis, underscoring a crucial role for TRIM28 in these endometrial pathologies." (PMID 37528140, 2023). "Because human endometriosis has the highest resemblance with the TRIM28 dependent transcriptome, we further examined TRIM28’s association with various types of endometriosis from the EndometDB, an endometriosis dataset with multiple subtypes of endometriosis." (PMID 37528140, 2023).
esophageal cancer (2 papers, 2019 to 2021). A primary or metastatic malignant neoplasm involving the esophagus. "However, there is no report on the correlation between TRIM28 and esophageal cancer." (PMID 30484263, 2019).
latent infection (2 papers, 2021 to 2025). "Our data support the hypothesis that Trim28 was enriched in the PFV LTR promoter and inhibited the PFV LTR-driven gene expression to establish PFV latent infection." (PMID 34903241, 2021).
leukemia (2 papers, 2022 to 2023). A malignant (clonal) hematologic disorder, involving hematopoietic stem cells and characterized by the presence of primitive or atypical myeloid or lymphoid cells in the bone marrow and the blood. "We also found several lysine residues in the coiled-coil domain were acetylated by MS analysis of immunoprecipitated TRIM28 in leukemia K562 cells, including K254, K261, K289, K304, K319, K366, and K377." (PMID 37372979, 2023). "These constructs were expressed in TRIM28 knockout human leukemia K562 cells to test their interaction with Gal4 DNA-binding domain (Gal4DBD)-KRAB." (PMID 37372979, 2023). "Our study shows that TRIM28 promotes cell proliferation and inhibits cell differentiation in leukemia cells as it is one anti-leukemic target." (PMID 35743282, 2022). "Taken together, we provide evidence to demonstrate the regulatory network of TRIM28-mediated cell growth and erythroid differentiation in K562 leukemia cells." (PMID 35743282, 2022). "To investigate the functional roles of TRIM28 in leukemia, we knocked out TRIM28 in K562 cells using CRISPR/Cas9 genome editing." (PMID 35743282, 2022). "This indicates that TRIM28 may be involved in the tumorigenesis of leukemia." (PMID 35743282, 2022). "Based on these results, more TRIM28-regulated miRNA and MAGE family expression can be extensively explored to build up a complete interacting network in leukemia, which is beneficial for diagnosis, therapy, and prognosis." (PMID 35743282, 2022).
lymph node metastasis (2 papers, 2019 to 2021). "Highly expressed TRIM28 in BC was associated with lymph node metastasis (P = 0.013), higher TNM stage (P = 0.013), and worse molecular subtype (P = 0.014)." (PMID 33817325, 2021). "TRIM28 overexpression was correlated with lymph node metastasis, advanced TNM stage, and poor molecular subtype." (PMID 33817325, 2021). "In the present study, we demonstrated that TRIM28 expression was significantly increased in ESCC and was associated with pTNM stage, invasive depth and lymph node metastasis." (PMID 30484263, 2019). "Moreover, the abnormal expression of TRIM28 was related to pTNM stage, invasive depth and lymph node metastasis (P < 0.05)." (PMID 30484263, 2019).
maturity onset diabetes (2 papers, 2024). "Along with TRIM28 and NOTCH3, one of our most interesting discoveries in the ART placentas concerned the prominent downregulation of imprinted DLK1 as well as the pathways of insulin secretion and maturity onset diabetes of the young, which came forth in the DNAm analyses." (PMID 39702541, 2024).
metastatic disease (2 papers, 2021 to 2022). "TRIM28 was also found overexpressed in BC and plays an important role in promoting metastatic disease, as TRIM28 depletion decreased the growth and metastatic potential of tumor xenografts." (PMID 34208621, 2021). "Overall, the three most highly expressed genes are TRIM28, TRIM44, and TRIM8 in the primary and metastatic tumors and normal tissues." (PMID 35928444, 2022).
tauopathies (2 papers, 2016 to 2021). "Taken together, our findings suggest that TRIM28 is aberrantly increased in cases of synucleinopathy and tauopathy and is pathologically associated with the nuclear accumulation of α-Syn and tau in a diseased state." (PMID 27779468, 2016). "In all cases of synucleinopathy and tauopathy, a greater proportion of TRIM28 accumulated in an insoluble form (Formic Acid fraction) than the more soluble form (RIPA fraction)." (PMID 27779468, 2016). "We performed bilateral lentiviral overexpression of TRIM28 in pre-symptomatic mouse models of synucleinopathy and tauopathy and found that injection with TRIM28, but not control lentivirus, worsened each aspect of neuropathology tested in both models." (PMID 27779468, 2016). "The unusual accumulation of TRIM28 in cases of synucleinopathy and tauopathy was a curious finding, though it remains solely an observation of correlative nature at this point." (PMID 27779468, 2016). "TRIM28’s crucial role in chromatin remodelling and its relationship with Tau support the hypothesis that TRIM28 may be a relevant factor that mediates Tau-dependent chromatin alterations in tauopathies." (PMID 34576308, 2021).
teratoma (2 papers, 2018 to 2025). A non-seminomatous germ cell tumor characterized by the presence of various tissues which correspond to the different germinal layers (endoderm, mesoderm, and ectoderm). "Similarly, the miRNA regulatory network associated with teratoma hub genes demonstrates distinct miRNA clusters targeting essential oncogenic regulators such as CDK1, HSP90AA1, HSPA4, TRIM28, and TOP2A." (PMID 40869426, 2025). "Conversely, the teratoma network was dominated by CDK1, HSP90AA1, TRIM28, and TOP2A—genes critically involved in mitotic progression, chromatin remodeling, and cellular stress response." (PMID 40869426, 2025).
testicular degeneration (2 papers, 2020 to 2024). "We established that Trim28 haploinsufficiency causes a gradual, age-dependent testicular degeneration." (PMID 32302554, 2020). "Of note, Trim28 deletion using the Stra8-Cre deleter strain yielded an initially unexpected milder testicular degeneration phenotype, which could be explained by the activation of Stra8-cre in response to retinoic acid in late undifferentiated spermatogonia, hence avoiding recombination in SSC." (PMID 32302554, 2020). "This suggests that testicular degeneration was independent of prenatal TRIM28 reduction." (PMID 32302554, 2020).
anorexia nervosa (1 paper, 2026). A disorder most often seen in adolescent females characterized by a refusal to maintain a minimally normal body weight, an intense fear of gaining weight, a disturbance in body image, and, in postmenarcheal females, the development of amenorrhea. "We explored the expressions of HERVs and TRIM28/SETDB1 in adolescents affected by anorexia nervosa (AN)." (PMID 42123339, 2026).
benign prostatic hyperplasia (1 paper, 2025). A non-cancerous nodular enlargement of the prostate gland. "To evaluate the protein expression of TRIM28 at varying stages of PCa progression, we analyzed TRIM28 IHC staining intensity in benign prostatic hyperplasia (BPH) (n = 16), Gleason score < 7 (n = 25), 7 [3 + 4] (n = 63), 7[4 + 3] (n = 26) and > 8 (n = 29)." (PMID 40519166, 2025).
brain tumors (1 paper, 2018). "A number of reports have also associated overexpression of TRIM28 with aggressiveness or poor outcome in adult cancers, specifically in breast, gastric, pancreatic, and brain tumors, although the mechanisms proposed are varied and perplexing." (PMID 30543698, 2018).
breast tumor (1 paper, 2017). "TRIM28 is up-regulated in breast tumors, and high TRIM28 expression is significantly associated with triple-negative breast tumors with stem cell-like features and poor survival." (PMID 27845900, 2017). "Although a considerable number of studies have revealed the roles of TRIM28 protein in experimental systems, little is known about the correlation between TRIM28 gene expression and clinical outcome in breast tumors." (PMID 27845900, 2017). "Therefore, we hypothesized that TRIM28 may play a role in aggressive breast tumor progression with stem cell-like features." (PMID 27845900, 2017).
chondrosarcoma (1 paper, 2024). A malignant cartilaginous matrix-producing mesenchymal neoplasm arising from the bone and soft tissue. "We found that the expression of UBE2S and TRIM28 was correlated with the survival of the patient with chondrosarcoma." (PMID 38267611, 2024).
chronic myeloid leukemia (1 paper, 2022). "In the chronic myeloid leukemia cell line K562, we edited TRIM28 using CRISPR/Cas9 technology, and the complete and partial knockout (KO) cell clones were obtained and confirmed using quantitative droplet digital PCR (ddPCR) technology." (PMID 35743282, 2022).
colitis (1 paper, 2018). Inflammation of the colon. "Compared with mice with WT T cells, those containing Trim28−/− T cells were ameliorated in colitis disease with less body weight loss." (PMID 29651155, 2018). "To assess the function of TRIM28 in naive T cells in vivo, we used a T-cell transfer colitis model in which Rag1−/− mice were injected with CD4+CD45RBhi naive T cells isolated from WT or Trim28−/− mice." (PMID 29651155, 2018). "Through using the in vitro culture system and T-cell transfer colitis, our study first identified a T-cell intrinsic effect of TRIM28 in directing Th17 differentiation." (PMID 29651155, 2018).
endometrial disorder (1 paper, 2023). A non-neoplastic or neoplastic disorder that affects the endometrium. "We found that TRIM28 deletion induced a gene signature in the mouse uterus and HESCs that positively correlated with several endometrial disorders, especially endometriosis." (PMID 37528140, 2023).
esophageal squamous cell carcinoma (1 paper, 2019). Esophageal squamous cell carcinoma (ESCC) is a type of esophageal carcinoma (EC) that can affect any part of the esophagus, but is usually located in the upper or middle third. "However, the role of TRIM28 in esophageal squamous cell carcinoma (ESCC) remains unclear." (PMID 30484263, 2019).
fibrosarcoma (1 paper, 2021). A malignant mesenchymal fibroblastic neoplasm affecting the soft tissue and bone. "Similar to human cancer cell lines, mouse fibrosarcoma cell line, L929 cells also showed necroptosis-dependent TRIM28 phosphorylation and increased mRNA level of immunostimulatory cytokine." (PMID 34419074, 2021).